CEACAM18 (CEA cell adhesion molecule 18)
Tractability: Antibody: UniProt predicts a signal peptide or a membrane-spanning region.
Gene: Protein-coding gene on chromosome 19 (51,478,539 to 51,491,301, forward strand). Ensembl gene ENSG00000213822.
Subcellular location (Human Protein Atlas): Midbody
Gene Ontology:
Biological process: heterophilic cell-cell adhesion; homophilic cell-cell adhesion
Cellular component: plasma membrane
Genetic constraint (gnomAD): Loss-of-function variants: 33 observed, 34.95 expected, observed/expected ratio (o/e) 0.94, 90% interval 0.71 to 1.26. The upper end of that interval is the gene's LOEUF score, 1.26, which puts it in group 5 of 6, group 1 being the genes least tolerant of losing a copy. Missense variants: 464 observed, 483.98 expected, observed/expected ratio (o/e) 0.96, 90% interval 0.89 to 1.03. Synonymous variants: 168 observed, 180.45 expected, observed/expected ratio (o/e) 0.93, 90% interval 0.82 to 1.06.
Homologues: Orthologues: macaque CEACAM18 (88% identical), mouse Ceacam18 (54% identical), rat Ceacam18 (52% identical), dog CEACAM18 (51% identical). Paralogues in human: CEACAM1 (25% identical), CEACAM5 (23% identical), CEACAM6 (23% identical), CEACAM8 (22% identical), CEACAM16 (21% identical), PSG8 (19% identical), CEACAM20 (19% identical), PSG6 (19% identical), PSG1 (18% identical), PSG3 (18% identical), PSG4 (18% identical), PSG7 (18% identical), and 12 more.
Diseases named in the same sentence as CEACAM18 in open-access papers:
CEACAM18 is named in the same sentence as 1 disease in open-access papers, as found by Europe PMC text mining. Sharing a sentence is not in itself a finding about the gene and the disease.
CEACAM18 shares sentences with these, for which no sentence is quoted: tumor (1 paper).